LRRK2 (leucine rich repeat kinase 2)
Diseases named in the same sentence as LRRK2 in open-access papers (continued):
Sharing a sentence is not in itself a finding about the gene and the disease.
depression (30 papers, 2011 to 2026). "Univariate and multivariate logistic modeling found significant associations between major depressive disorder, perinatal depression, natural childbirth, LRRK2 genotype, B12 deficiency, total hysterectomy, and increased PD severity." (PMID 37277346, 2023). "This study concluded that there is greater involvement of the limbic system in patients with LRRK2 G2019S mutation, and depression and hallucinations are more frequent among them." (PMID 36106206, 2022). "Depression and other neuropsychological abnormalities are more frequent in PD patients with LRRK2 G2019S mutation." (PMID 36106206, 2022). "Centrophobism is indicative of emotional abnormalities, such as anxiety and depression, both of which are often associated with PD, and was also displayed by the LRRK2-G2019S mice." (PMID 34779396, 2021). "PD patients carrying LRRK2 mutations are more susceptible to depression." (PMID 39219304, 2024). "We found that depression and vaginal birth (Part I); depression and perinatal depression (Part II); LRRK2 mutation status, B12 deficiency, and total hysterectomy (Part III) were significantly associated with a moderate/severe PD phenotype compared to a mild phenotype." (PMID 37277346, 2023). "In addition, transgenic mice harboring the G2019S (glycine to serine substitution at amino acid 2019) mutation have been shown to display anxiety/depression-like behavior, despite the paradoxical phenotype of G2019S mutation gain of function and loss of LRRK2 in KO mice." (PMID 31555076, 2019). "Our miRNA-TFs-hub genes network advances several novel molecular targets like PTGS2, LRRK2, miR-146a-5p, and miR-181c-5p, which might contribute to the development of novel diagnostic, monitoring, and therapeutic strategies in (hypovitaminosis D-related) depression." (PMID 38256187, 2024). "In the present study, inhibition of LRRK2 by treatment with the antagonist PF-475 showed antidepressant-like activity against mTBI-induced depression-like behaviors and restored the changes in the Cu/NMDAR system." (PMID 37048114, 2023). "As a further measure of the potential role of LRRK2 on stress-related processes, we assessed 5-HT1A levels in the hippocampus, which has been implicated in depression and anxiety that accompany PD." (PMID 31174552, 2019). "Reports on depression, anxiety and psychiatric involvement in LRRK2 related PD are equivocal in the literature." (PMID 31164863, 2019). "Available data suggest thathyposmia, depression and constipation can be present in the premotor stage of LRRK2-PD and IPD." (PMID 26177462, 2015). "In contrast, depression and worse color discrimination have been reported to occur more frequently in LRRK2-PD." (PMID 26177462, 2015). "Depression, anxiety and hallucinations were present in our LRRK2 patients at a frequency similar to that reported in the literature." (PMID 25330404, 2014). "Smell loss, depression, constipation and EDS were reported to develop before OMS in more than 40% of the LRRK2-PD patients in whom these symptoms were present at the time of examination." (PMID 25330404, 2014). "Hyposmia, depression, constipation and excessive daytime sleepiness, were reported to occur before the onset of classical motor symptoms in more than 40% of LRRK2-PD patients in whom these symptoms were present at the time of examination." (PMID 25330404, 2014). "Similarly, both middle-aged (43–52 weeks) and old (65–83 weeks) LRRK2 mice also showed to exhibit significant reductions in their sucrose preference confirming depression-like behavior in this PD model." (PMID 39763579, 2024). "Direct inhibition of LRRK2 by PF-06447475 significantly reduces depression-related symptoms in mice, suggesting that LRRK2 might be a valuable therapeutic target in MDD." (PMID 38256187, 2024). "In conclusion, this study suggests that LRRK2 may represent a new therapeutic strategy for patients with depression-related symptoms." (PMID 37048114, 2023).
depression (continued). "The aim of this study was to investigate the role of LRRK2 in reducing depression-related symptoms after mTBI and to determine whether inhibition of LRRK2 mediated by PF-06447475 could have antidepressant effects." (PMID 37048114, 2023). "Aside from WSHFs, non-sex-specific factors, like major depression disorder, LRRK2 mutation carrier status, and B12 deficiency, were seen amongst women with a more severe phenotype compared to those with a mild PD phenotype." (PMID 37277346, 2023). "With a reported prevalence of 42 %, depression is, however, common in LRRK2-PD." (PMID 38835904, 2022). "Symptomatic LRRK2 mutation carriers share non-motor features with individuals with sporadic PD, including hyposmia, constipation, impaired color discrimination, depression, and sleep disturbance." (PMID 32457695, 2020). "It has been shown that LRRK2-knockout (KO) mice display anxiety/depression-like behavior." (PMID 31555076, 2019). "The HADS subscore for depression was similar between LRRK2-PD and IPD, but higher than HS." (PMID 25330404, 2014). "Like in IPD, disturbances such as hyposmia, depression, constipation and excessive daytime sleepiness may antedate the onset of classical motor symptoms in LRRK2-G2019S-PD." (PMID 25330404, 2014). "Smell loss and depression were reported to occur at variable time intervals before OMS but constipation and EDS frequently were estimated to occur more than 10 years before OMS in most LRRK2-PD." (PMID 25330404, 2014). "Our CytoHubba analysis identified six hub genes (PECAM1, TLR2, PTGS2, LRRK2, HCK, and IL18), all significantly upregulated in both depression and hypovitaminosis D, with PTGS2 having the highest inference score and reference count." (PMID 38256187, 2024). "LRRK2-PD patients were older and had higher UPDRS-I-IV scores, HADS depression subscore, early awakening, PSQI score, PSQI ≥6, PDSS-2 score and more benzodiazepine intake." (PMID 26177462, 2015). "A substantial proportion of our LRRK2-PD patients reported that several NMS, such as hyposmia, depression, constipation, or EDS, had been present before OMS." (PMID 25330404, 2014). "Moreover, impairment of hippocampal neurogenesis has been described in animal models of memory loss and depression suggesting that mutant LRRK2 may also contribute to non-motor symptoms of PD." (PMID 21695257, 2011). "LRRK2 p.G2019S carriers were more likely to report urinary frequency/urgency symptoms compared to noncarriers, and reported diagnoses of depression at similar prevalence to noncarriers." (PMID 40926580, 2025). "Similar rates of depression between IPD and LRRK2-PD have been observed." (PMID 38835904, 2022). "LRRK2 p.G2019S PD reported less nocturia and orthostatic hypotension than GBA1 p.N409S PD and noncarriers with PD, and less erectile dysfunction and depression relative to noncarriers with PD." (PMID 40926580, 2025). "Current active depression and current treatment with antidepressive drugs were more frequent in IPD than in LRRK2-PD, but these differences were not statistically significant." (PMID 25330404, 2014). "In addition, although there are several gene variants associated with the development of non-motor symptoms in PD patients (e.g., LRRK2, SNCA, Parkin, and VPS35), only a few studies have explored their effects on depression-like behavior in mice." (PMID 35645772, 2022).
Anxiety (28 papers, 2014 to 2026). Intense feelings of nervousness, tension, or panic often arise in response to interpersonal stresses. "We analyzed a subset of brain regions implicated in anxiety-like behaviors and that exhibit high levels of LRRK2 expression." (PMID 39328984, 2024). "Recently, it has been revealed that LRRK2 is related to anxiety/depression-like behavior, implying an association between LRRK2 and stress." (PMID 31555076, 2019). "Age-dependent impairments in anxiety/depressive-like behaviour starting from 6–11 months were identified in LRRK2 G2019S mice from 2 studies and circadian rhythm dysfunction was noted at 6–11 months in another study." (PMID 36551782, 2022). "It has been reported that monogenic PD patients with mutations in the α-synuclein, LRRK2, VPS35, Parkin, PINK1, DJ-1 and GBA genes exhibit psychiatric disturbances such as depression and anxiety." (PMID 34145553, 2021). "In the LRRK2-G2019S PD mice model, anxiety/depression-like behavior was observed before the onset of motor dysfunction, accompanied by upregulation of the serotonin 5-HT1A receptor." (PMID 34145553, 2021). "Anxiety symptoms were reported coincidentally or developing after OMS in most LRRK2-PD cases but more frequently before OMS in IPD." (PMID 25330404, 2014). "At the end of the 12-week experiment, anxiety-like behavior was evaluated by the light/dark box test; compulsive-like behavior by Marble burying, transcriptional regulation of genes Lrrk2, Tlr4, Nfat, Drd1, Drd2, Il6, Il1β, Il10, and iNOS by RT-qPCR; and inflammatory markers by flow cytometry." (PMID 37063320, 2023). "Of note, sleep onset insomnia in LRRK2-PD was not linked to features such as age, gender,PD severity and duration, anxiety, and cognitive status." (PMID 26177462, 2015). "For instance, BAC mice overexpressing human G2019S LRRK2 showed faster walking speed (and anxiety-like behavior) in the open field whereas human G2019S overexpressors under the Thy1 or the TetO CaMKII promoters showed transient improvement in rotarod performance or increased exploratory behavior." (PMID 25107341, 2014). "Similarly, 3 LRRK2-PD patients were under anxiety treatment but only 2 had active anxiety." (PMID 25330404, 2014). "Interestingly, relatives of LRRK2-PD (n = 142, independent of mutation carrier status) present with a worse motor score and anxiety compared to 172 controls, implying that other environmental or non-LRRK2 genetic modifiers might influence the penetrance of LRRK2 p.G2019S-PD." (PMID 33494262, 2021). "Collectively, these behavioral data indicate decreased anxiety phenotypes and increased motor impairments in α-syn PFF-injected LRRK2 G2019S transgenic mice." (PMID 30927072, 2019).
Tremor (22 papers, 2008 to 2025). An unintentional, oscillating to-and-fro muscle movement about a joint axis. "LRRK2 mutation carriers have been reported to have a more prominent tremor and slightly slower disease progression, although the presentation of disease is largely overlapping with iPD." (PMID 31733655, 2019). "The patients with LRRK2 p.G2019S homozygous mutations had middle-aged onset, tremor-dominant and mixed type of tremor, and rigid akinesia, similar to heterozygous patients." (PMID 30333048, 2018). "LRRK2 G2019S mutation is associated with more dystonia (OR = 4.655, p = 0.042) and sleep complaints (OR = 2.4, p = 0.045) but less tremor (OR = 0.3, p = 0.011)." (PMID 28465860, 2017). "The higher incidence of tremor in the patients with mutations in LRRK2 than the QSBB was significant (odds ratio [OR] 1·49, 95% CI 1·1–2·0; p<0·003)." (PMID 18539534, 2008). "Furthermore, differences in disease severity (tremor and motor fluctuations), age of onset, brain pathology, and drug response have been reported among LRRK2 variants." (PMID 37371062, 2023). "In addition we could exclude that G20195 mutations in the LRRK2 gene, which associate with tremors, were present in our cohort population." (PMID 23400498, 2013). "These self-report measures indicated that motor symptoms, particularly tremor and postural instability, are the most prominent features of LRRK2 G2019S carriers with PD." (PMID 38804604, 2024). "MD-319 (LRRK2 p.G2019S) started with tremors at age 5; by 14 years old, he presented bradykinesia and a hoarse voice." (PMID 36233161, 2022). "Four studies assessed the relationship between LRRK2 G2385R status and the tremor phenotype of PD patients." (PMID 30123490, 2018). "Although earlier studies considered tremor as the predominant feature of LRRK2 carriers, in a recent study, tremor was observed less in patients with LRRK2 p.G2019S than in idiopathic PD." (PMID 25391693, 2014). "In our series, the phenotypes are overlapping but the LRRK2 subjects have less tremor." (PMID 28465860, 2017). "In terms of initial presentation, the only difference found between PARK-LRRK2, PARK-SNCA, and PARK-VPS35 was that the most common sign and symptom in both PARK-SNCA (31.2%) and PARK-VPS35 patients (15.9%) was bradykinesia, while in LRRK2 variant carriers, it was tremor (52.5%)." (PMID 39962078, 2025). "Thus dopaminergic expression of LRRK2-G2019S induces bradykinesia and tremor as well as akinesia." (PMID 29214211, 2017). "As RBD had been associated with a non-tremor predominant phenotype, and a higher rate of motor complications in PD patients, our findings may further confirm an important relationship between RBD and motor phenotypes in PD patients with LRRK2 variants." (PMID 27330837, 2016). "LRRK2 G2019S carriers have less tremor than noncarriers do as first symptom (26.8% versus 52.5%, corrected-p = 0.03) and exhibited less of the tremor-dominant phenotype than noncarriers (corrected-p = 0.009)." (PMID 28465860, 2017). "Our principle finding is that expressing LRRK2 forms with increased kinase activity (G2019S, I2020T) in sets of dopaminergic neurons that include the TH-VUM is sufficient to induce akinesia, bradykinesia, and tremor in the fly PER." (PMID 29214211, 2017). "In particular, numerous monogenic neurodegenerative, neuropathic and metabolic diseases manifest with tremor often accompanied by signs of other movement disorders, especially of a dystonic (e.g. ANO3, SGCE), ataxic (e.g. PPPP2R2B, ATX3, TBP) or parkinsonian (e.g. LRRK2, FMR1, ATX3) type." (PMID 39346806, 2024).
Lewy body disease (21 papers, 2006 to 2026). "The Parkinson’s Progression Marker Initiative’s brain autopsy program reported severe Lewy body disease in all LRRK2 mutation carriers among 17 brain donations." (PMID 41050048, 2025). "Here, we report a PD case with LRRK2 G2385R wherein a typical diffuse Lewy body disease pathology with mild gliosis, possibly caused by increased LRRK2 kinase activity in the brain was observed." (PMID 35931783, 2022). "In addition, the correlation between genotype and phenotype needs to be clarified further, since some genes can be responsible for different pathologies, such as the LRRK2 mutation, which is implicated in PD, Lewy Bodies Disease or Multiple System Atrophy." (PMID 40141040, 2025). "Reported severe Lewy body disease in all LRRK2 mutation carriers among 17 brain donations." (PMID 41050048, 2025). "Interestingly, a high predictive accuracy of the MDS criteria has also been detected in a cohort study in 121 patients with idiopathic RBD (PPV 81%; for conversion into PD or dementia with Lewy bodies over 4 years) and a cohort of leucine-rich repeat kinase 2 (LRRK2) mutation carriers (PPV 47%–67%)." (PMID 35184752, 2022). "Another study has reported that LRRK2 localizes to enlarged lysosomes or vacuoles in brains of Lewy body disease patients, raising the possibility that CASM-mediated lysosomal targeting of LRRK2 is activated in pathological conditions." (PMID 38227290, 2024). "Moreover, PD dementia (PDD) and dementia with Lewy bodies (DLB) have also been associated with the presence of intraneuronal tau aggregation, as in tauopathies, suggesting a role for LRRK2 in mediating tau spread." (PMID 34200180, 2021). "Based on data from the Mayo Clinic brain bank, 59% (30/51) of cases with LRRK2 mutations had Lewy body disease, while the remaining LRRK2 cases had tau or TDP-43 pathology or nonspecific substantia nigra degeneration (unpublished data)." (PMID 34922583, 2021). "We show that non-inclusion aggregated α-synuclein in the form of particulate PLA signal is dominant in the LRRK2 cases, while both Lewy-like and particulate PLA signal is found in late-stage Lewy body disease." (PMID 40314782, 2025). "Furthermore, LRRK2 cases displayed prominent particulate PLA signal in pontocerebellar tracts and inferior olivary nuclei in the brainstem, which was not seen in idiopathic Lewy body disease cases." (PMID 40314782, 2025).
REM sleep behavior disorder (21 papers, 2012 to 2025). A disorder characterized by episodes of vigorous and often violent motor activity during rem sleep (sleep, rem). "These subjects include GBA, LRRK2, and parkin mutation carriers, subjects with a family history of PD, cases of late-onset idiopathic hyposmia, and patients with idiopathic REM sleep behavior disorder (RBD)." (PMID 33432494, 2021). "This correlation with disease stage was also evident in asymptomatic LRRK2 mutation carriers, as well as patients with idiopathic REM sleep behavior disorder (iRBD)." (PMID 33477387, 2021). "Further studies that examine the co-immunostaining of a-synuclein and LRRK2 in those with preceding gastrointestinal symptoms, brainstem dysfunctional symptoms of rapid eye movement sleep behavior disorder or having LRRK2 risk variants are needed to confirm our hypothesis." (PMID 35126095, 2021). "Those who are potentially at risk for PD (e.g., leucine-rich repeat kinase 2 (LRRK2) carriers, those with rapid eye movement sleep behavior disorder, anosmia, constipation, abnormal positron emission tomography (PET) scans, etc.)may be excellent candidates for primary prevention." (PMID 22550611, 2012). "GBA1 p.N409S PD was associated with the highest burden of non‐motor symptoms, including REM sleep behavior disorder and cognitive/memory deficits, and LRRK2 p.G2019S with the lowest." (PMID 40926580, 2025). "We discovered that hundreds of proteins were upregulated in the CSF, blood, or urine of PD patients, prodromal PD patients with DAT deficit and REM sleep behavior disorder or anosmia, and non-manifesting genetic carriers of LRRK2 and GBA mutations." (PMID 38467937, 2024). "In this respect, carriers of dominant PD genes, such as leucine-rich repeat kinase 2 (LRRK2) mutations, or subjects with REM sleep behavior disorder (RBD) are ideal candidates to evaluate the detection of preclinical/premotor PD by means of nuclear medicine or MRI." (PMID 31405186, 2019). "REM sleep behavior disorder (RBD) was diagnosed in three LRRK2-PD." (PMID 26177462, 2015). "For example, in PD patients with mutations in the Leucine-rich repeat kinase 2 (LRRK2) gene, the disease progresses slower than those without mutations and are less frequently affected by non-motor symptoms, including olfaction, REM-sleep behavior disorders, and cognitive dysfunction." (PMID 36979316, 2023). "Probable REM sleep behavior disorder (RBD) had a considerably higher rate in GBA1-PD than in LRRK2-PD, whereas none of the GBA1-LRRK2-PD cases noted RBD." (PMID 39766872, 2024).